PPARG (peroxisome proliferator activated receptor gamma)
Diseases named in the same sentence as PPARG in open-access papers (continued):
Sharing a sentence is not in itself a finding about the gene and the disease.
atherosclerosis (continued). "A previous report has revealed that nobiletin attenuated lipid accumulation and the extent of atherosclerotic lesions and further alleviated atherosclerosis by inhibiting lipid uptake via the PPARγ/CD36 pathway." (PMID 40832599, 2025). "In response to acute cerebrovascular damage, PPAR-γ (peroxisome proliferator-activated receptor gamma) plays a critical role in regulating glucose trafficking, protection against atherosclerosis, and modulating the immune-inflammatory cascade." (PMID 40149423, 2025). "PPARG, a ligand-activated transcription factor, plays critical roles in adipocyte development, insulin sensitivity, lipid metabolism, and atherosclerosis in tissues such as adipose, macrophages, intestines, and ovaries." (PMID 40028534, 2025). "Dysregulation of PPARγ signaling is associated with increased intracellular cholesterol accumulation, MDFC formation, and the progression of atherosclerosis." (PMID 40867523, 2025). "PPARγ plays a key role in inhibiting atherosclerosis, which suggests that ALDH1A3 is related to atherosclerosis by suppressing ferroptosis and enhancing PPARγ expression." (PMID 40176913, 2025). "A recent study also identified endothelial PHACTR1 as a novelcorepressor of peroxisome proliferator-activated receptor gamma (PPARγ),promoting atherosclerosis in regions exposed to disturbed flow." (PMID 41524047, 2025). "Homoeriodictyol and hesperidin-7-O-β-D-glucopyranoside are found to significantly increase the level of PPARγ protein, providing new candidates for treatment of atherosclerosis." (PMID 38699583, 2024). "In this study, we identified that Ash2l as an important regulator in the process of atherosclerosis, enhanced the expression of scavenger receptors through the activation of PPARγ." (PMID 38280036, 2024). "According to them, the strong therapeutic effects of PPARα and PPARγ agonists benefit systemic lipid levels, glucose homeostasis, and atherosclerosis." (PMID 39062500, 2024). "The QiShenYiQi pill hinders atherosclerosis by stimulating cholesterol retrogradation through the PPARγ-LXRα/β-ABCA1 pathway, consequently diminishing lipid deposition." (PMID 38952541, 2024). "This research focused on improving atherosclerosis by modulating the PPARG/CD36 pathway in macrophages." (PMID 38468335, 2024). "The primary gene whose mutation can cause multistep disorders leading to the development of metabolic syndrome and atherosclerosis is the peroxisome proliferator-activated receptor gene γ (PPARG)." (PMID 39062500, 2024). "This research underscores anti-inflammation as a crucial biological process in AA treatments for atherosclerosis, with PPARγ potentially serving as a key target." (PMID 39065817, 2024). "Drugs targeting the PPARG/CD36 signaling pathway are promising therapeutic options for the therapy of atherosclerosis." (PMID 38468335, 2024). "In atherosclerosis, PPARG promoted the differentiation of peripheral blood monocytes to tissue macrophages and macrophage infiltration." (PMID 38468335, 2024). "In experimental models, treatment with peroxisome proliferator-activated receptor gamma (PPARγ) agonists improved insulin sensitivity and inhibited the development of atherosclerosis." (PMID 38791064, 2024). "Mechanistic insights into capsaicin’s actions involving TRPV1 and PPARγ pathways provide further rationale for exploring its clinical applications in managing atherosclerosis and related complications." (PMID 39339767, 2024). "Activation of PPARγ signaling by formononetin reduces inflammation, oxidative stress, and apoptosis, thereby limiting endothelial damage in oxLDL-induced atherosclerosis." (PMID 37833942, 2023). "According to recent research, quercetin has been shown to increase adiponectin secretion and prevent atherosclerosis by regulating factors, such as PPARG." (PMID 37334066, 2023).
atherosclerosis (continued). "Given the importance of PPARγ in EC dysfunction and the role of EC disorders in atherosclerosis progression, it is essential that we understand the mechanisms behind PPARγ signaling in endothelial function." (PMID 37833942, 2023). "Both Nrf2 and PPARγ are important sensors of lipid disturbances and stress responses, and they have been involved in macrophage lipid accumulation and atherosclerosis." (PMID 37432260, 2023). "Recently, TSA was found to target C/EBPα/PPARγ axis and induce acetylation of C/EBPα to alleviate atherosclerosis." (PMID 38031118, 2023). "MiRNA-130a suppression can protect against atherosclerosis through inhibiting inflammation by regulating the PPARγ/NF-κB expression." (PMID 36888629, 2023). "Thiazolidinediones (TZDs), synthetic ligands of PPARγ, have been shown to reduce the incidence of atherosclerosis." (PMID 37833942, 2023). "We also explore the potential use of endothelial PPARγ-targeted agents in the prevention and treatment of atherosclerosis." (PMID 37833942, 2023). "In a previous report, macrophage NCOR1 has been shown to prevent atherosclerosis via activation of PPARγ." (PMID 38030614, 2023). "Taken together, these findings revealed the protective value of oridonin against atherosclerosis through FABP4/PPARγ pathway." (PMID 37905351, 2023). "Recently, we demonstrated that the deletion of macrophage NCOR1 aggravates atherosclerosis by promoting CD36-triggered foam cell formation via PPARG derepression." (PMID 37349757, 2023). "The role of NCOR1 in macrophages in atherosclerotic cardiovascular disease is complex and has been shown to have a protective function during atherosclerosis, but an increase in inflammatory cytokines is also observed in response to PPARγ agonist stimulation." (PMID 38030614, 2023). "In macrophages, H2S-mediated peroxisome proliferator activated receptor gamma (PPARγ) inhibition also inhibits C-X3-C chemokine fractalkine (CX3CL1) signaling in the context of atherosclerosis in ApoE−/− mice." (PMID 37373103, 2023). "PPARγ has multiple biological functions and is important for regulating metabolism, controlling inflammation, improving atherosclerosis, inhibiting tumors, and regulating immune processes." (PMID 36874004, 2023). "On the contrary, c9,t11-CLA and t9,t11-CLA reduce atherosclerosis and improve insulin sensitivity by enhancing PPARγ and LXRα." (PMID 37367916, 2023). "For example, t10,c12-CLA worsens atherosclerosis and insulin sensitivity by inhibiting the expression of peroxisome proliferator-activated receptor gamma (PPARγ) and liver X receptor alpha (LXRα)." (PMID 37367916, 2023). "A previous study focused on the effects of NAMPT on alleviating atherosclerosis by regulating PPARγ pathway-based monocyte differentiation." (PMID 36604715, 2023). "HDAC3 protects against atherosclerosis through inhibition of inflammation via the microRNA-19b/PPARγ/NF-κB axis in ox-LDL treated HUVECs and ApoE−/− mice." (PMID 38031118, 2023). "It is worth noting that PPARγ plays an important role in atherosclerosis and regulates the activity of LXRα and NF‐κB." (PMID 37905351, 2023). "Clinical trials and post-market surveillance studies have established the effectiveness of PPARγ agonists in preventing atherosclerosis progression." (PMID 37238730, 2023). "Another PPARγ agonist, rosiglitazone, decreases autoantibody production and prevents atherosclerosis and renal diseases in mouse models of SLE by upregulating adiponectin." (PMID 36293172, 2022). "Many preclinical and clinical research studies have shown that PPARγ agonists reduce atherosclerosis and intimal hyperplasia." (PMID 35656103, 2022).
atherosclerosis (continued). "Previous studies also pointed out that PPARG can inhibit the inflammatory response and the proliferation of smooth muscle cells to protect against atherosclerosis." (PMID 35265101, 2022). "Acetylation of PPARγ at K268/K293 increases atherosclerosis through upregulating ABCA1, ABCG1, and NcoR but inhibiting PRDM16, while deacetylation of PPARγ at K268 and K293 alleviates atherosclerosis." (PMID 35309069, 2022). "Peroxisome proliferator activated receptor γ (PPARγ) is a key transcription factor for cholesterol metabolism in macrophages and its role in regulating atherosclerosis related foamy macrophages (FMs) formation has been well-studied." (PMID 35432274, 2022). "Quercetin can inhibit atherosclerosis-induced myocardial infarction (MI), heart failure, and hypertension by upregulation of PPARγ and the signaling cascades involved, including the antioxidant pathway and the downregulation of inflammatory cytokines." (PMID 36092543, 2022). "Although the mechanism of PPARγ in regulating lipid efflux has been well-studied in atherosclerosis, in tuberculosis, it still needs to be further investigated." (PMID 35432274, 2022). "However, PPARγ phosphorylation mediated by different enzymes, conformational changes at different sites can cause the recruitment response of different cofactors, its role in atherosclerosis and its mechanism need to be further studied, and also provide ideas for the drug design of PPAR ligand." (PMID 35309069, 2022). "Peroxisome proliferator-activated receptor gamma (PPARγ), a promising therapeutic target for atherosclerosis, plays a dual role in regulating cholesterol efflux and endothelial cell inflammation." (PMID 36518993, 2022). "In recent years, more and more studies have found that PPARγ plays an important role in protecting atherosclerosis." (PMID 36518993, 2022). "The significant contribution of PPARγ in the limitation of the progression of atherosclerosis through multiple mechanisms is well studied and reviewed elsewhere." (PMID 35203258, 2022). "In conclusion, our study revealed that QHZYF attenuates atherosclerosis via targeting PPARγ-mediated PPARγ/LXRα/ABCA1-ABCG1 and PPARγ/NF-κB p65 pathways to regulate cholesterol efflux and endothelial cell inflammation." (PMID 36518993, 2022). "miR-130a promotes inflammation which accelerates disease progression in atherosclerosis by downregulating the expression of PPARG." (PMID 35990982, 2022). "Some related studies have shown that the ABCG1 gene is itself a direct target of LXRα and LXRα is a selective target of PPARγ in the context of atherosclerosis." (PMID 35432274, 2022). "In an in vitro atherosclerosis cell model, allicin, leonurine, etc. have been shown to promote lipid efflux through the PPARγ-LXRα-ABCG1 axis." (PMID 35432274, 2022). "The ligand-inducible transcription factors PPARγ is highly expressed in macrophages, and is known to control macrophage inflammation, polarization, and lipid metabolism in atherosclerosis plaques." (PMID 35590369, 2022). "It has been reported that genetic disruption or pharmacological inhibition of the AT1R attenuates atherosclerosis and improves endothelial function in diabetic ApoE−/− mice via the PPARγ pathway." (PMID 35990823, 2022). "Additional actions of PPARγ include the regulation of adipokines and inflammatory mediators expression, M1/M2 macrophage polarization, atherosclerosis and bone formation." (PMID 33799988, 2021). "12-HEPE was identified as a dominant ω3 fatty acid metabolite in serum of mice fed with linseed oil, and acted as anti-atherosclerosis molecules by inhibiting foam cell formation in a PPARγ-dependent manner." (PMID 34001916, 2021). "Peroxisome proliferator-activated receptor gamma (PPARG) is involved in the transcription of atherosclerosis and related diseases." (PMID 33628326, 2021).
atherosclerosis (continued). "Conversely, its activation reduces inflammation, inhibits apoptosis, and improves endothelial function, making PPARγ agonists an interesting therapeutic option for the treatment of dyslipidemia, atherosclerosis, and CV diseases." (PMID 33158204, 2020). "Taken together, these findings suggest that BCA is protective against atherosclerosis by inhibiting lipid accumulation and inflammatory response through the PPARγ/LXRα and PPARγ/HO-1 pathways." (PMID 33959213, 2020). "Baicalin potentially exerts anti-atherosclerosis effects through the PPARγ–LXRα–ABCA1/ABCG1 pathway by promoting cholesterol efflux from macrophages and delaying the formation of foam cells." (PMID 33321972, 2020). "Consistent with this, synthetic ligands of PPARγ have been shown to reduce atherosclerosis in mouse models." (PMID 33574817, 2020). "Berberine was found to suppress atherogenesis through activation of AMPK-dependent UCP2 expression and stabilize atherosclerosis plaques in hyperhomocysteinemia mice via activation of peroxisome proliferator-activated receptor gamma (PPARγ)." (PMID 32566106, 2020). "LPA can also bind the nuclear peroxisome proliferator-activated receptor gamma (PPARγ) and initiate early stages of atherosclerosis." (PMID 32560330, 2020). "In the context of atherosclerosis, PPARγ regulates transcriptional responses of macrophages invading atheroscleroic plaques." (PMID 33574817, 2020). "PPARγ agonists are used to treat patients with atherosclerosis, and several studies report the beneficial effect of PPARγ agonists as therapeutic target for MS63,64, providing evidence for a beneficial role of microglia in NAWM." (PMID 30867424, 2019). "For example, PPARγ has been found to provide additional benefits for cardiovascular homeostasis and related functional problems including atherosclerosis, restenosis, and hypertension." (PMID 31018521, 2019). "Recent advances on the emerging role of CD36 and GHRP hexarelin in regulating PPARγ downstream actions with benefits on atherosclerosis, hepatic cholesterol biosynthesis and fat mitochondrial biogenesis are summarized here." (PMID 29883404, 2018). "Taken together, ginsenoside 20(S)-Rg3 protected against atherosclerosis by reversing the M1 polarization to the M2 phenotype and limiting intraplaque inflammatory response, which was achieved by PPARγ." (PMID 29867472, 2018). "PPARγ, a key heterodimer partner with RXRs, was shown to participate in the regulation of cholesterol metabolism and exert protective effects against atherosclerosis in humans, mice and rabbits." (PMID 30154509, 2018). "Lysophospholipids act as mediators via the activation of cell surface GPCRs, and as intracellular second messengers through PPARγ activation and inhibition in diseases such as atherosclerosis, dementia, and spinal cord injury." (PMID 29258184, 2017). "Statins, which are used in the treatment of atherosclerosis result in an increase in PPARγ activity by activating extracellular signal-regulated kinase (ERK) 1/2 and p38 mitogen-activated protein kinase (MAPK) pathways." (PMID 28243251, 2017). "There are many studies which demonstrate the beneficial role of PPARγ in limiting the progression of atherosclerosis as well as the acceleration of atherosclerosis with the knockout of PPARγ in macrophages." (PMID 28243251, 2017). "The role of PPARγ activation in macrophage cholesterol homeostasis has been established, and studies suggest that PPARγ is involved in the development of atherosclerosis." (PMID 27869741, 2016). "The upregulated PPARγ can prevent atherosclerosis by improving the endothelial cells function, inhibiting the proliferation and migration of vascular smooth muscle, and stabilizing the plaques." (PMID 26844229, 2015).
atherosclerosis (continued). "PPARγ is a ligand-activated transcription factor of the nuclear hormone receptor family and the activation of PPARγ improves vascular endothelial function, prevents the progression of intima-media thickening and atherosclerosis." (PMID 25748432, 2015). "Ciglitazone and rosiglitazone effectively suppressed DCs maturation, retarded vascular injury, attenuated cell apoptosis and atherosclerosis formation through activating peroxisome proliferator-activated receptor γ (PPARγ)." (PMID 25388834, 2015). "In early lesions, PPARG was identified as a specific master regulator of the PCL-responsive atherosclerosis TF-regulatory network, whereas in mature and advanced lesions, the specific master regulators were MLL5 and SRSF10/XRN2, respectively." (PMID 24586211, 2014). "It has been reported that genetic disruption or pharmacological inhibition by telmisartan of the AT1R attenuates atherosclerosis and improves endothelial function in diabetic ApoE-/- mice via the PPARγ pathway." (PMID 24485356, 2014). "In one study, simvastatin, from the statin family of drugs used commonly for atherosclerosis management, was able to activate a peroxisome-proliferator response element in a PPARγ dependent manner to produce effects similar to those achieved by PPARγ agonists." (PMID 25191225, 2014). "The beneficial effects of sesamin on hypercholesterolemia, inflammation, peroxidation and PPARγ expression therefore make it a promising candidate for the prevention and treatment of atherosclerosis." (PMID 24914897, 2014). "Treatment with PPARγ agonists such as rosiglitazone can efficiently prevent the occurrence and development of atherosclerosis." (PMID 24914897, 2014). "The effect of PPARγ activation on macrophage differentiation became even clearer in the field of atherosclerosis, where monocytes developed into enhanced M2 phenotype after PPARγ activation." (PMID 23554810, 2013). "Because DKO mice, in contrast to single KO mice, are characterized by decreases in Pparα and Pparγ and accelerated atherosclerosis, we selected DKO mice to investigate the effect of fenofibrate and rosiglitazone." (PMID 23620818, 2013). "Genetic disruption or pharmacological inhibition of the AT1R attenuates atherosclerosis and improves endothelial function in diabetic ApoE−/−-mice via the PPARγ pathway." (PMID 23374104, 2013). "Recent studies have shown that PPARγ has the inherent capacity to regulate expression of macrophage chemokine receptors CX3CR1 in the lipid-mediated inflammation process of atherosclerosis lesions." (PMID 22815945, 2012). "Adiponectin is also known to be upregulated by PPARγ and treatment with PPARγ agonists results in decreased atherosclerosis." (PMID 21941676, 2011). "PPARγ-deficient mice have provided clues to an antiatherogenic role of PPARγ since these mice showed a significantly impaired lipid homeostasis in the arterial wall and enhanced atherosclerosis development." (PMID 20871817, 2010). "This review provides an overview about the role of PPARγ as a possible therapeutic target approaching major, severe diseases, such as sepsis, cancer, and atherosclerosis." (PMID 21057731, 2010). "The insulin-sensitizing drugs TZDs, as PPARγ agonists, have beneficial effects on serum lipids in diabetic patients and have also been shown to inhibit the progression of atherosclerosis in animal models." (PMID 19737384, 2009). "The peroxisome proliferator-activator receptor PPARγ plays an essential role in vascular biology, modulating macrophage function and atherosclerosis progression." (PMID 19888469, 2009). "PPARγ has other effects on atherosclerosis includinginduction of apoptosis in monocytes, inhibition of VSMC proliferation, and suppression of matrix metalloproteinase-9 expression." (PMID 19277201, 2008).